CD44 (CD44 molecule (IN blood group))
Diseases named in the same sentence as CD44 in open-access papers (continued):
Sharing a sentence is not in itself a finding about the gene and the disease.
breast carcinoma (continued). "Our results show that blocking CD44 or RGD-dependent integrins on the surface of breast cancer cells abrogates migration toward BMCM." (PMID 28498874, 2017). "IL-6 is a direct regulator of breast CSC self-renewal and IL-6/JAK2/STAT3 pathway is more active in CD44(+)CD24(-/low) breast cancer cells compared with other tumor cell types and its inhibition blocks the growth of xenografts." (PMID 28270211, 2017). "These authors also showed that several isoforms of CD44, expressed on murine mammary carcinoma cells, provide cell surface docking receptors for proteolytically active MMP9." (PMID 28191466, 2017). "In breast cancer, CSCs are characterized by high CD44 and low CD24 marker expression, while CD133 and CD44 are used for glioblastoma CSCs." (PMID 28883835, 2017). "Next, we investigated the role of these cell surface proteins in the migration of breast cancer cells using an anti-CD44 functional blocking antibody or an Arg-Gly-Asp (RGD) peptide." (PMID 28498874, 2017). "These stem-like breast cancer cells can be isolated using specific markers including a CD44+CD24- phenotype and/or high aldehyde dehydrogenase activity (ALDHhi)." (PMID 28498874, 2017). "In this study, we demonstrated the heterogeneity of CSCs expressing different CD44 isoforms in breast cancer, and identified a CSC subpopulation with enhanced lung metastasis capacity." (PMID 28300837, 2017). "Broadly, CD44+/CD24− population profile is recognized in breast cancer for the presence of tumor initiating cells." (PMID 28240233, 2017). "Breast cancer cells that undergo EMT acquire a basal-like CD44+/CD24- stemness phenotype characterized by a greater capacity for tumor self-renewal and early onset of distant metastasis." (PMID 29207686, 2017). "This study aimed to analyze the effect of extracellular alkalinization on metabolism and survival of human CD24-/CD44+ breast cancer stem cells (BCSCs)." (PMID 28746471, 2017). "In breast cancer cells, exosomal miR-23b promoted dormancy and decreased CD44 surface abundance, a characteristic marker of breast cancer stem cells (CSCs)." (PMID 28402944, 2017). "We also carried out IHC staining to assess the protein abundance of DACH1 and CD44 in luminal-type and basal-like breast cancer tissues." (PMID 28659634, 2017). "Specifically, breast cancer cells with a CD44+ phenotype have been shown to have increased adherence to human bone marrow endothelial cells." (PMID 28498874, 2017). "In the present study, we evaluated the effect of CB1 agonist and antagonist on proliferation and invasion potential of (CD44+/CD24-/low/ESA+) human breast cancer stem cells which were derived from MDA-MB-231 and their parental cells." (PMID 29552056, 2017). "It has also been reported that highly tumorigenic breast cancer stem cells (CD44+CD24-/low) are generated through activation of the Ras pathway in EMT, providing a direct link between EMT and cancer stem cells." (PMID 28114432, 2017). "CD44 functioned as an oncoprotein and knockdown of CD44 remarkably attenuated the migration and invasion of breast cancer cells MDA-MB-231 and Hs578T by modulating c-Src transcription." (PMID 28659634, 2017). "For instance, TGF-β1 induces EMT by the transactivation of EGFR/EGF signaling through HA/CD44 in lung and breast cancer cells." (PMID 29261154, 2017). "Recent studies have demonstrated the role of TRIM28 protein in autophagy, a stress-induced process that has been suggested to maintain the CD44+/CD24−/low breast cancer stem-like phenotype." (PMID 27845900, 2017). "In conclusion, this study confirmed that DACH1 and CD44 inversely related in breast cancer, different grade tumors and different subtypes." (PMID 28659634, 2017). "In breast cancer, the CD44+/CD24−/low cells from patients were found to be more tumorigenic than the CD44+/CD24+ cells when implanted into the mammary fat pads of the immunodeficient nonobese diabetic (NOD)/severe combined immunodeficient (SCID) mice." (PMID 29062075, 2017).
breast carcinoma (continued). "In order to assess the prognostic value of DACH1 and CD44 in breast cancer, a meta-analysis enrolling a total of 19 published Gene Expression Omnibus (GEO) databases and including 3574 breast cancer patients was performed." (PMID 28659634, 2017). "The transmembrane cell adhesion molecule, CD44, is known to promote tumorigenic signaling in breast cancer." (PMID 28778177, 2017). "The previous studies showed that Klf4 is essential for maintaining CSC-like cells in colon CSC-enriched spheroid cells and breast cancer stem cells, whereas Klf4-mediated suppression of CD44 signaling negatively modulated the stemness of pancreatic cancer." (PMID 29212199, 2017). "By analyzing the immunohistochemical images and immunoreactive scores of BMP-2, CD44, and Rb proteins in each sample, we confirmed that BMP-2 expression was positively correlated with CD44 expression in the breast carcinoma cohort." (PMID 28725489, 2017). "Using SERS nanoparticles that target HER2 and CD44 in breast cancer cells, we demonstrate labeling of fixed cells with high specificity that correlates well with fluorescent labels." (PMID 28667313, 2017). "The findings were confirmed by animal studies which showed that chronic alcohol (12 months) exposure increased CD44 positive cells in the mammary tumors of MMTV-neu transgenic mice which was accompanied by the increased metastases in the lung and colon." (PMID 29156633, 2017). "The expression of EMT-associated genes in CD44+/CD24− cells isolated from normal human breast tissue, and from primary breast cancer, showed that many of the EMT transcription factors were expressed more so when cells had stem cell-like features." (PMID 27429011, 2016). "Breast cancer cells with CD44+/CD24low/- surface phenotype have tumor initiating properties with pluripotency characteristics and invasive capacity." (PMID 26934679, 2016). "In breast cancer, CD44+/CD24- cells or ALDH1+ cells have both been reported to retain CSC characteristics." (PMID 27285982, 2016). "This nanoparticle delivery system was able to target different CD44-positive cancer cell lines, and to selectively kill CD44-positive cancer cells present in pancreatic and breast cancer cell lines." (PMID 27679576, 2016). "In defining the molecular basis governing this tissue selectivity, we identified the selective packaging of CD44 in MDR breast cancer-derived EVs." (PMID 26938523, 2016). "The CD44-targeted conjugate demonstrated acute cell killing of breast cancer cells with high CD44 expression." (PMID 27302409, 2016). "TG2 overexpression in MCF7 cells increased the surface expression of breast cancer stem cell marker CD44, and IL-1β stimulation of MCF7_TG2 breast cancer cells further increased CD44 expression." (PMID 27609180, 2016). "Nanosystems derived from many HA derivatives transfected siRNA efficiently into CD44 overexpressing cancer cells including MDA-MB468 breast cancer cells." (PMID 27679576, 2016). "HA-mediated CD44 signaling plays important roles in the regulation of solid tumor malignancies such as breast cancer." (PMID 27070574, 2016). "The expression of CD44+/CD24-/low has been extensively used as markers for breast cancer stem cells." (PMID 27416801, 2016). "An important feature of breast cancer stem cells is the expression of the surface markers CD44 and CD24." (PMID 27120585, 2016). "Actually, we found that the CD44-positive subpopulation in primary breast cancer cells (KBr2, KBr3 and KBr4), showed higher levels of AurkA and wnt3a mRNAs as well as increased migratory ability, compared to CD44-negative cells." (PMID 27341528, 2016). "When mouse breast cancer cells were treated with pacilitaxel and epirubicin in serum-free condition and then maintained in suspension culture, they became mostly CD44+CD24- cells together with higher tumorigenic potential." (PMID 27766946, 2016). "Our findings suggest the presence of an interactive network of proteins namely, ERM and CD44 with P-gp, in breast cancer cells." (PMID 26938523, 2016).
breast carcinoma (continued). "Over-expression of OCT4 is found in lung cancer-derived CD133- and CD44-positive cells, anticancer drug-selected breast cancer cells, which exhibit enhanced resistance to chemotherapeutic agents." (PMID 27816965, 2016). "Using an ERK1/2 inhibitor to mimic the inhibition of ERK1/2 activity by WNT5A, we confirmed a link between ERK1/2-MAPK signaling and CD44 expression in breast cancer cells." (PMID 27623766, 2016). "Metastasis and aggressiveness have been correlated with CD44 expression in breast cancer and renal cell carcinoma." (PMID 26821610, 2016). "Our results raise the possibility of CD44+/24- being a good prognostic marker, one which would allow treatment effects and outcomes to be predicted in patients with recurrent breast cancer." (PMID 27768764, 2016). "We observed a dose-dependent decrease in the expression of pAKT, thereby validating our finding that WNT5A indeed inhibits the CD44-AKT signaling pathway in breast cancer cells." (PMID 27623766, 2016). "The step-wise neoplastic transformation of stem cells provides an in vitro model of breast cancer progression, including the emergence of breast cancer stem cell marker CD44+/CD24−." (PMID 27807451, 2016). "It was demonstrated that human breast cancers contain a cell population with stem cells properties bearing the surface markers CD24−/CD44+/lin−." (PMID 26759169, 2016). "Based on the function of CD44 as a CSC marker for breast cancer cells and the link between EMT and stemness, we determined the effects of etoposide on several CSC features." (PMID 27009862, 2016). "We used siRNA silencing of Ezrin, Radixin, Moesin and CD44 to evaluate the role of each protein in regulating P-gp function in drug-resistant breast cancer cells." (PMID 26938523, 2016). "Anti-CD44 antibodies-conjugated gold nanorods have been used to sensitize MCF-7 breast cancer that overexpresses the CD44 surface marker." (PMID 27200096, 2016). "We analyzed the in vitro activity of etoposide as a CD44 antagonist using MDA-MB-231 breast cancer cells, > 95% of which express high levels of CD44." (PMID 27009862, 2016). "Based on our literature review, we expect to observe an increase in CD44+/CD24−/low cells in breast cancer cells cultured in PCL scaffolds." (PMID 27120585, 2016). "To investigate the differences caused by the loss of Llgl1 and the different populations that are observed, we evaluated the cells using breast cancer stem cell markers CD44, CD49f, and CD24." (PMID 27542214, 2016). "In human breast cancers, the rare CD44+/CD24−/low subpopulation shares properties with normal stem cells, including increased reproductive capacity and the ability to give rise to diverse cell lineages." (PMID 27379202, 2016). "Our previous studies in EVs shed from multidrug resistant breast cancer cells showed a selective packaging of Ezrin, Radixin, Moesin and CD44 in resistant breast cancer cell-derived EVs." (PMID 26938523, 2016). "Subsequently, we validated our findings by Western blotting, demonstrating that WNT5A expression does indeed inhibit the expression of CD44 protein in WNT5A-expressing breast cancer cell lines." (PMID 27623766, 2016). "Previous studies have found that tumor initiating cells in breast cancer exhibit a characteristic profile of the across cell surface markers CD44 and CD24." (PMID 27303921, 2016). "The experimental data presented herein corroborate the relationship between the expression levels of WNT5A and CD44 in clinical breast cancer samples and their relation to disease-free survival and cumulative survival of patients with breast cancer." (PMID 27623766, 2016). "We also again observe a selective packaging of CD44 in resistant breast cancer-derived EVs consistent with our previous findings." (PMID 26938523, 2016). "CD44 expression has been reported higher in breast cancer stem cells under conditions of hypoxia than normoxia, and HIF-1α was found to control CD44 expression in these cells." (PMID 27347945, 2016).
breast carcinoma (continued). "Breast cancer stem-like cells (BCSCs) exhibiting a CD44+/CD24-/lin- phenotype as well as the expression and activity of aldehyde dehydrogenase 1 (ALDH1) are detected in DCIS." (PMID 27589390, 2016). "In breast cancer, EMT has been associated with CSCs characteristics including self-renewal ability and the expression of stem cell-associated cell subpopulation CD44+/CD24–/low." (PMID 27842518, 2016). "Identification of breast CSCs from tumor samples or breast cancer cell lines has been based mainly on CD44+/CD24−/low or ALDH+ phenotypes." (PMID 26757880, 2016). "We have demonstrated that MCF7 breast cancer cells from the TS subpopulation are enriched in cells with a CD44+/CD24− phenotype, which is characteristic of breast CSCs13." (PMID 26752044, 2016). "As can be seen in this study, canine and human breast cancer efficiently formed mammospheres, consisting of CD44+/CD24low/- cells, which confirms the cancer stem cell phenotype." (PMID 26934679, 2016). "Specifically, we showed the selective packaging of Ezrin-Radixin-Moesin (ERM) and CD44, among other proteins, in EVs shed from drug-resistant breast cancer cells." (PMID 26938523, 2016). "We next assessed the level of BCSCs in the different breast cancer subtypes by examining the expression levels of the cancer stem cell surface markers CD44 and CD24." (PMID 27759034, 2016). "Further analyses indicate that HA binding to CD44 stimulates PKCε activation and Nanog phosphorylation, which in turn, activates Nanog signaling-regulated miR-21 production in breast cancer cells." (PMID 27070574, 2016). "CSCs in breast cancer have been characterized as CD44+/CD24−, and/or positive for aldehyde dehydrogenase 1 (ALDH1)." (PMID 26973433, 2016). "We have previously shown that salinomycin gave the highest selective activity against CD44+/CD24− cells at ~ IC25 in the breast cancer cell line JIMT-1." (PMID 26906175, 2016). "The binding of scaffold CP7 to MDA-MB-468 breast cancer cells which overexpress CD44 was determined by immunofluorescence." (PMID 27874025, 2016). "Recently, our preliminary data indicate both Stat-3/Nanog and JNK/c-Jun pathways can be simultaneously activated in the upregulation of miR-21 expression during HA/CD44-mediated signaling in both breast cancer cells and head and neck cancer cells." (PMID 27070574, 2016). "Like mammosphere-forming capacity, the ability to exclude Hoechst 33342, expression of CD44, CD24, ESA and CD133, and high aldehyde dehydrogenase (ALDH) activity has been associated with the tumorigenic subfraction of breast cancer." (PMID 26595803, 2016). "The CD44+/CD24-/ESA+ subpopulation has been identified as being significantly enriched in the breast cancer stem cell population." (PMID 26821678, 2016). "These HA based siRNA delivery systems thus portend to be promising for systemic targeted therapeutics against CD44 overexpressing breast cancer stem-like cells and metastatic lesions." (PMID 27679576, 2016). "The synergistic action of SAL and PTX, and their specificity toward the targeted cells, resulted in high cytotoxicity against the CD44+ breast cancer stem-like cells." (PMID 27679576, 2016). "The CD44 expressed in some breast cancer cells displays unique properties to promote tumor cell-specific characteristics." (PMID 27070574, 2016). "CD44+/CD24−/low breast cancer CSCs, isolated from MDA-MB-231 and MCF7 mammospheres, were relatively more resistant to radiation and this was associated with lower levels of ROS after radiation." (PMID 26682001, 2016). "A study in 2006 assessed MCF7 and MDA-MB-231 breast cancer cell lines grown in 2D culture compared to CD44+ve/CD24−ve subpopulations grown in mammosphere assays after exposure to different amounts of radiation." (PMID 27189371, 2016). "We however, found much higher CD44 expression in the CA breast cancer cells that further increased with NO treatment." (PMID 27473585, 2016).
breast carcinoma (continued). "The CD44 molecule is predominantly involved in adhesion, but also characterizes the CSC sub-population in human breast cancer, denoted by the CD44+/CD24low/− phenotype." (PMID 27835603, 2016). "In breast carcinomas, the CD44+/CD24− cell subset is thought to represent a stem cell-like population and is enriched in tumorigenic stem/progenitor cells." (PMID 27270657, 2016). "Our siRNA data suggest that CD44 per se plays an important role in mediating the aggressive phenotype of acquired endocrine-resistant breast cancer cells." (PMID 27379207, 2016). "We show that, Radixin and CD44 are required for regulating P-gp drug efflux in resistant breast cancer cells at a functional level." (PMID 26938523, 2016). "This delivery system increased the efficacy of DOX by six times for eliminating CD44+ breast cancer stem-like cells compared with free DOX." (PMID 27679576, 2016). "In breast cancer, CD44+/ESA+/CD24lo cells are relatively insensitive to conventional chemotherapy and to radiation." (PMID 26880941, 2016). "A recent study using breast cancer biopsy tissues showed that chemotherapy led to an increased percentage of CD44+/CD24+ cells, consistent with increased clone formation ability." (PMID 27323403, 2016). "CD44 promotes migration and proliferation through interaction with many signaling molecules and it is a promising target for therapy in breast carcinoma." (PMID 27683033, 2016). "CD44 is known to regulate PI3K/AKT signaling in breast cancer, and this pathway plays an important role in cell survival, invasion and metastasis." (PMID 27623766, 2016). "In the present study, we showed that WNT5A affects breast cancer cell migration and invasion by inhibiting CD44 expression and downstream AKT signaling." (PMID 27623766, 2016). "Cell surface markers such as CD44+/CD24-/low have been used to separate mammary stem/progenitor cells from differentiated breast cancer cells." (PMID 27529753, 2016). "HA binding to CD44 stimulates miR-21 expression has been reported in several cancer cells including breast cancer cells and head and neck cancer cells." (PMID 27070574, 2016). "Similar work demonstrated the chemotherapy resistant nature of the CD24-/CD44+ enriched population of breast cancer cells." (PMID 27028405, 2016). "CD44+/CD24− cells isolated from some human breast cancer cell lines (e.g., MCF-7) and patient tumors demonstrate many stem-cell like properties in vitro and in vivo." (PMID 27379202, 2016). "First, increased CD44 expression has been correlated with breast cancer cell metastasis and a poor prognosis." (PMID 27623766, 2016). "The only published study that directly manipulated OPN receptors in human breast cancer utilized a CD44 neutralizing antibody in MDA-MB-231 and they observed that antibody mediated suppression of CD44 signaling inhibited migration." (PMID 27282619, 2016). "We also confirmed that miR-199a-5p significantly decreased the CD24-/CD44+ cell population (p = 0.0015), which is a well-reported subpopulation of breast cancer cells to have stem/progenitor cell properties." (PMID 27842518, 2016). "Our results demonstrated that miR-199a-5p indeed inhibited the breast cancer cell stemness by decreasing the CD24-/CD44+ population and ALDH activity." (PMID 27842518, 2016). "SLUG upregulation was reported to promote stemness in breast cancer cells, with increased CD44 and Jagged-1 expression, mammosphere growth, and extracellular matrix invasiveness." (PMID 28116318, 2016). "Comparison of the gene expression profiles of CD44+ and CD24+ cells revealed that CD44+ cells specifically expressed multiple stem cell markers, which expression correlate with poor survival outcomes in breast cancer patients." (PMID 27759034, 2016). "H460 H-INV cells also express lower mRNA levels of CD24, which is proposed to be one of the molecular features when combined with CD44 expression (as CD44+/CD24low) for breast cancer stem cells." (PMID 27634890, 2016).